EZH2 (enhancer of zeste 2 polycomb repressive complex 2 subunit)
Diseases named in the same sentence as EZH2 in open-access papers (continued):
Sharing a sentence is not in itself a finding about the gene and the disease.
lung cancer (continued). "EZH2 overexpression in lung cancer is common and associated with aggressive tumor characteristics, advanced stage and poor prognosis." (PMID 28672805, 2017). "Overall, the combined HR for all 10 eligible studies evaluating EZH2 overexpression on OS was 1.68(1.42–1.93), suggesting that EZH2 overexpression was associated with poor prognosis for lung cancer." (PMID 26754405, 2016). "Combined hazard ratios suggested that EZH2 overexpression was associated with poor prognosis of overall survival (OS) (HR = 1.68, 95% CI: 1.42–1.93) in patients with lung cancer." (PMID 26754405, 2016). "The underlying mechanism of EZH2 on lung cancer development will demonstrate the new pathway of lung cancer development, invasion and metastasis." (PMID 26903164, 2016). "Overexpression of EZH2 has been associated with several cancers, including prostate cancer, breast cancer, bladder cancer, and lung cancer." (PMID 27582065, 2016). "Overexpression of EZH2 is associated with tumor growth, metastasis and poor prognosis in multiple cancer types, including lung cancers." (PMID 26362062, 2015). "Recently, a couple of transcription factors and lncRNAs, such as NF-YA, hMOF and lncRNA-Sox2ot, have been implicated in EZH2 overexpression in ovarian, oral tongue squamous cell carcinoma and lung cancer." (PMID 26484567, 2015). "Furthermore, elevated EZH2 levels in lung cancer are associated with reduced responsiveness to treatment, complicating disease management." (PMID 40070571, 2025). "Additionally, FAK inhibitors have been reported to induce cellular senescence in lung cancer cells, potentially by downregulating the expression of enhancer of zeste homolog 2 (EZH2), a protein associated with cancer cell proliferation and survival." (PMID 39976799, 2025). "Also, overexpression of EZH2 is linked with a worse prognosis in lung cancer, particularly showing higher levels in late‐stage NSCLC than in early stages." (PMID 39083441, 2025). "For instance, EZH2, found to be overexpressed in lung cancer tissues compared to normal lung tissues, is significantly associated with the development and progression of lung cancer." (PMID 38525426, 2024). "Relatively limited literature exists on histone modifications, with one notable example being the capacity of NRF2 to facilitate rapid cell proliferation in EZH2 (enhancer of zeste homolog 2)-deficient lung cancer cells, which potentially contributes to therapeutic resistance." (PMID 39061847, 2024). "The risk of lung cancer brain metastasis of G allele carriers has increased by 2.1241 times.This is the first study to discover the relationship between gene polymorphism in the exon region of the EZH2 gene and the risk of brain metastasis in lung cancer." (PMID 38764053, 2024). "We need to further increase the sample size, increase the number of loci, and conduct functional research on its locus polymorphism, thus providing more reliable evidence for the relationship between EZH2 SNP polymorphism and the occurrence and development of brain metastasis in lung cancer." (PMID 38764053, 2024). "Specific targets, such as PRMT1, KDM6B, CARM1, BRD4, and EZH2, have been shown to be associated with malignant phenotypes of lung cancer, influencing cell proliferation and metastatic processes (regulation of epithelial–mesenchymal transition and cell invasion)." (PMID 36233212, 2022). "Similarly, inhibiting EZH2 has been reported to enhance the sensitivity of the pan‐PI3K inhibitor copanlisib in lung cancer cells harbouring mutated or amplified PIK3CA when the manuscript was in preparation." (PMID 35604910, 2022). "We anticipate analogous results may be obtained in EGFR-mutant lung cancers that lose RB1 since these variants are likely to up regulate EZH2." (PMID 32292420, 2020).
lung cancer (continued). "The present results also suggested that EZH2 inhibitors might have a role in the treatment of melanoma that expresses high EZH2 and low KDM6A as loss of KDM6A sensitizes bladder and lung cancer cells to treatment with EZH2 inhibitors." (PMID 32731355, 2020). "In conclusion, our findings indicated that EZH2 promoted lung cancer metastasis and macrophages infiltration via upregulation of CCL5, which might be the underlying mechanism of EZH2‐induced lung cancer cell progression." (PMID 31855281, 2020). "Lung tumors with KDM6A loss was more sensitive to EZH2 inhibition, indicating lung cancer patients with specific histone methylation features might benefit from specific epigenetic therapy." (PMID 30002791, 2018). "For example, altered expression of EZH2 was proved to be associated with the risk of lung cancer." (PMID 28938616, 2017). "As determined in our meta-analysis, we concluded that EZH2 overexpression was associated with poor overall survival in lung cancer, this effect appears also significant when the analysis is restricted in Asian population, lung AC and stage I patients, but not among Caucasians." (PMID 26754405, 2016). "Moreover, Huaier extract also caused apoptosis in lung cancer cells via a miR-26b-5p-EZH2-mediated approach." (PMID 26229542, 2015). "Such divergence in Cdc2 expression also suggests that the therapeutic efficacy of EZH2 silencing in clinical therapy may also be dependent on the underlying specific lung cancer pathology." (PMID 24745014, 2014). "Similarly, the expression of lncRNA HOTAIR is significantly increased in lung cancer, and it can promote the transcriptional activity of β‐catenin by binding to various proteins associated with the Wnt signaling pathway, such as EZH2, thereby enhancing the oncogenic effects of the Wnt pathway." (PMID 39991629, 2025). "Importantly, our discovery that EZH2 coordinates EMT–MET is in consonance with previous reports studying lung cancer cells where it has been shown that the loss of function of EZH2 hinders repression of mesenchymal genes during MET, and reduces tumour colonisation capacity in mouse models." (PMID 39174513, 2024). "Besides, EZH2 has been reported to activate signaling pathways associated with the maintenance of lung cancer stem cells, while inhibition of EZH2 could enhance the sensitivity of lung cancer toward chemotherapy." (PMID 34124072, 2021). "Thus, we aimed to validate the underlying mechanism of the effects of EZH2 on lung cancer." (PMID 31855281, 2020). "The molecular mechanisms associated with EZH2 expression, generate a dysregulation of cell apoptosis, mesenchymal transition, and cell invasiveness in bronchial epithelial cells, encouraging the progression of airway inflammation toward lung cancer in COPD patients." (PMID 31666665, 2019). "Thus, LAT1 and EZH2 appear to be functionally linked with a more aggressive lung cancer phenotype." (PMID 30103560, 2018). "EZH2 may exert its oncogenic function, at least in part, by silencing tumor-suppressive miRNAs, and further investigation is required to verify the association between H3K27me3 and miRNA expression in lung cancer." (PMID 24348521, 2013). "Larger prospective studies with standardized scoring systems are warranted to validate these findings and to clarify the clinical utility of c-MYC and EZH2 as potential prognostic and therapeutic biomarkers in lung cancer." (PMID 41928013, 2026). "In lung cancer, the expression of EZH2 is often upregulated, leading to elevated levels of H3K27me3 and silencing of many tumor suppressor genes." (PMID 41394878, 2025). "Stimulation of TAMs showed PRMT1-mediated EZH2 methylation, promoting lung cancer proliferation and metastasis by modulating oncogene methylation through EZH2." (PMID 40358164, 2025).
lung cancer (continued). "LINC01088 suppresses p21 and promotes cell proliferation by interacting with EZH2 in non‐small cell lung cancer." (PMID 40000422, 2025). "Tazemetostat targets EZH2, a histone methyltransferase often overexpressed in cancer, including lung cancer." (PMID 40191732, 2025). "In lung cancer cells, EZH2 has been found to induce the activity of hypoxia-inducible factor 1α, thereby promoting the expression of PD-L1, establishing a positive correlation." (PMID 40308579, 2025). "Experiments show that ubiquitously enforced EZH2 expression in mice can induce the occurrence of lung cancer, indicating its carcinogenicity." (PMID 40028035, 2025). "They then examined the correlation between MEG3 expression levels and EZH2 recruitment at specific genomic loci in A549 and LC-2/ad lung cancer cell lines." (PMID 40149464, 2025). "Inhibitors targeting DNA methyltransferase (DNMT) in gliomas and melanoma. enhancer of Zeste homolog 2 (EZH2) in lung cancers, and lysine demethylase 5 (KDM5) in colorectal cancers are known to restore STING expression." (PMID 40789065, 2025). "In lung cancer, abnormal expression of multiple HMTs leads to disrupted methylation patterns, among which EZH2 and SETD2 are the most representative key regulators." (PMID 41394878, 2025). "EZH2 is overexpressed in numerous cancers, including lung cancer, where it appears to promote oncogenesis through silencing transcription (via trimethylation of H3K27) and blocking differentiation." (PMID 38612589, 2024). "Here, we found that NOP2 and ALYREF had a co-regulatory role in the stability of EZH2 mRNA in lung cancer." (PMID 39013911, 2024). "From lung cancer to the progression of brain metastasis, the positive sites of EZH2 RNA in situ hybridization gradually increase in signal intensity from within the nucleus to outside the nucleus." (PMID 38764053, 2024). "EZH2 is critical to cancer initiation/progression and is frequently overexpressed in lung cancer and many other human cancers." (PMID 37992808, 2024). "EZH2 is widely overexpressed in human lung cancer tissues and cells, and its suppression inhibits 2D lung cancer cell growth as shown here and by others." (PMID 37992808, 2024). "RNA in situ immunohybridization showed that EZH2 mRNA expression was gradually high in lung cancer adjacent tissues, lung cancer tissues and lung cancer brain metastasis tissues." (PMID 38764053, 2024). "Despite this limitation, this work demonstrates several mechanisms through which EZH2 inhibition can boost ICI responses in lung cancer." (PMID 38265267, 2024). "In lung cancer brain metastasis tissue, T-tests were performed on the expression levels of EZH2 between CG genotype and CC genotype." (PMID 38764053, 2024). "Further research on the relationship between EZH2 gene frequency and prognosis of lung cancer brain metastasis needs to be expanded in the future." (PMID 38764053, 2024). "In a word, our research highlights the significant role of NOP2 in LUAD and offers novel mechanistic insights into the NOP2/ALYREF/EZH2 axis, which holds promise as a potential target for lung cancer therapy." (PMID 39013911, 2024). "Taken together, these findings suggest that NOP2 can promote the development of lung cancer in vivo by regulating EZH2." (PMID 39013911, 2024). "It revealed that there was a significant difference in the G553C genotype of EZH2 between lung cancer brain metastasis tissues and lung cancer tissues (p = 0.045)." (PMID 38764053, 2024). "The results of transwell assay similarly demonstrated the important effects of ALYREF and EZH2 on the migration and invasion ability of lung cancer cells." (PMID 39013911, 2024). "Immunohistochemical detection of EZH2 expression was performed on brain metastatic tissues, primary lung cancer lesions, and adjacent tissues of different genotypes of lung cancer." (PMID 38764053, 2024).
lung cancer (continued). "Our recent study of human lung cancers showed that macrophages and plasma cells can also predominate in tumors, and it will be important to test EZH2 inhibition in the context of diverse tumor immune microenvironments moving forward." (PMID 38265267, 2024). "The level of EZH2 expression correlates positively with the malignancy and poor prognosis in lung cancer." (PMID 38525426, 2024). "As anticipated, the overexpression of NOP2 facilitated the in vivo growth of lung cancer cells, whereas the introduction of sh-EZH2 mitigated this promoting effect." (PMID 39013911, 2024). "Compared with the adjacent lung tissues of lung cancer patients, the expression level of EZH2 was significantly increased in lung cancer tissues, and the expression level was higher than that of brain metastases from lung cancer patients." (PMID 38764053, 2024). "This indicates that the HIF-1α/miR-101/EZH2 network is active even under normal O2 circumstances in lung cancer cells (HCC4006, HCC461, and HCC1171) that are subjected to increased VEGF stimulation and high levels of VEGFR-2 expression." (PMID 38911968, 2024). "We previously reported that high EZH2 expression is related to poor outcomes in patients with stage I non‐small cell lung cancer, large tumor size, and enhanced cellular proliferation." (PMID 39400978, 2024). "According to the Welch ANOVA test, the expression of EZH2 in the brain tissues of 40 lung cancer patients with brain metastasis and 20 lung cancer patients with lung cancer and adjacent lung cancer tissues in three groups of samples will be analyzed." (PMID 38764053, 2024). "The enhancer of zeste homolog 2 (EZH2) protein is a lysine methyltransferase that is commonly overexpressed in lung cancer cells and exerts oncogenic effects via its methyltransferase activity." (PMID 39113127, 2024). "In contrast, knockdown of ALYREF inhibited the elevation of EZH2 expression triggered by NOP2 overexpression as well as the enhancement of the migratory invasive ability of lung cancer cells." (PMID 39013911, 2024). "We analyzed EZH2 and E‐cadherin expressions in lung cancer cell lines and tumor tissues from 34 SCLC patients and confirmed EZH2 siRNA‐mediated EMT inhibition." (PMID 39400978, 2024). "Compared with adjacent lung cancer tissues, the expression level of EZH2 in lung cancer tissues is significantly increased (p < 0.0001), and the expression level is higher than that in brain metastasis tissues of lung cancer patients (p = 0.0309)." (PMID 38764053, 2024). "These discoveries unveil a novel regulatory pathway through which NOP2 exerts its oncogenic influence—at least in part by upregulating EZH2 expression in lung cancer." (PMID 39013911, 2024). "Further analysis was conducted on the expression levels of EZH2, three different genotypes of GG, CG, and CC, in three groups of samples: lung cancer brain metastasis tissue, lung cancer tissue, and lung cancer adjacent tissue." (PMID 38764053, 2024). "The results showed that the decrease in EZH2 expression triggered by NOP2 knockdown as well as the antitumor phenotype of lung cancer cells were suppressed by overexpression of ALYREF." (PMID 39013911, 2024). "It was previously shown that treating lung carcinoma or ovarian cancer cells with TGFβ enhanced EZH2 inhibitor-mediated increases in EMT gene expression." (PMID 39561122, 2024). "Similar inverse relationship between the levels of K20-methylation and S21-phosphorylation of EZH2 were also observed in human lung carcinoma H1299 cells." (PMID 38346162, 2024). "EZH2 was highly expressed in lung cancers with positive KRAS expression, and the correlation was significant in lung adenocarcinoma (r = 0.3129, p < 0.001)." (PMID 37069494, 2023). "Here the authors show haplo- and full-insufficiency of EZH2 drive divergent phenotypes in lung cancer." (PMID 36670102, 2023). "The N‐terminal glycine of EZH2 undergoes myristoylation in lung cancer cells, thereby instigating liquid–liquid phase separation (LLPS)." (PMID 38034101, 2023).
lung cancer (continued). "The overexpression of EZH2 and elevation of H3K27me3 in solid cancers, including breast, gastric, endometrial, ovarian, melanoma, bladder, kidney, colorectal, and lung cancers, as well as hematological malignancies such as T-cell and B-cell lymphomas." (PMID 36672374, 2023). "The results of TCGA database revealed that the expression of EZH2 was lower in normal tissues than in lung cancer tissues (p < 0.05)." (PMID 37069494, 2023). "According to the current study, LINC00969 promotes gefitinib resistance in lung cancer by simultaneously binding to EZH2 and METTL3." (PMID 37156816, 2023). "The expression level of EZH2 is high in lung cancer, particularly in SCLC, which is associated with poor therapeutic effects, making it a mark for lung cancer treatment." (PMID 37543653, 2023). "The top three human cancer types with the most significant EZH2 mRNA expression were lung cancer, colorectal cancer, and head and neck cancer." (PMID 36545914, 2023). "miR-124 is a tumor suppressor in lung adenocarcinoma associated with epithelial-to-mesenchymal (EMT) phenotypes and targets the enhancer of zeste homolog 2 (EZH2) to suppress lung cancer cells like A549, H1299, SPC-A1, and H1975." (PMID 37508353, 2023). "By enhancing the expression of CCL5, EZH2 facilitated the recruitment and aggregation of macrophages in lung cancer, led to the invasion of tumor cells, and accelerated the epithelial–mesenchymal transition (EMT) process of pancreatic cancer cells." (PMID 36545914, 2023). "Enhancer of zeste homolog 2 (EZH2) is an important epigenetic regulator, and is associated with the malignant progression of lung cancer." (PMID 36629984, 2023). "In our study, EZH2 was highly expressed in lung cancers with positive KRAS expression, and the correlation was significant in lung adenocarcinoma (r = 0.3129 and p < 0.001)." (PMID 37069494, 2023). "EZH2, a methyltransferase mediating H3K27me3 modification in the cell nucleus, is generally highly expressed in lung cancer." (PMID 37543653, 2023). "When EZH2 is inhibited, the quantity of M2 decreases, thereby preventing the progression of lung cancer." (PMID 37513975, 2023). "A recent experiment has shown that miRNA-92b as a tumor-suppressor role and binds to 3′-UTR of EZH2 to reduce its expression, impairing proliferation and metastasis of lung cancer cells." (PMID 35236381, 2022). "It has been reported that miRNA-21 promotes the expression level of EZH2 and enhances the progression of CSCs to provide resistance to radiotherapy and chemotherapy in lung cancer cells." (PMID 35236381, 2022). "MiRNA-21, which is recognized as a potential serum biomarker during epigenetic therapy in MDS, is also an up-regulator of EZH2 in human lung cancer stem cells, whereas miRNA-148a has recently been recognized as a down-regulator of DNMT1 in AML cells." (PMID 36555712, 2022). "Immunohistochemistry shows that active FAK signaling corresponds with the activation of the EZH2-mediated signaling cascade in lung-cancer-cells-derived tumor tissues." (PMID 36009484, 2022). "This idea was raised by the discovery of the role of EZH2 in promoting metastasis in cancer cells in “in vitro” experiments performed in human lung cancer cell lines." (PMID 36135315, 2022). "In PCa and lung cancer, we have seen the presence of a small population of cancer stem cells with stem cell-like characteristics, which overexpress EZH2 and selectively downregulate miR-34a and let-7b expression." (PMID 36135315, 2022). "We also discovered changes in the expression of new targets of FZD9, including EZH2, IL1β, and VEGFA, all of which are associated with lung cancer." (PMID 35924166, 2022). "EZH2 was also highly expressed in the lung cancer with positive KRAS expression, exhibiting a positive correlation, as well as with the expression of BRAF, especially in lung squamous cell carcinoma." (PMID 36195655, 2022). "In Section 4, we discussed the immunosuppressive role of EZH2 and provide lung cancer as an example." (PMID 36230683, 2022).